ARID1A (AT-rich interaction domain 1A)
Diseases named in the same sentence as ARID1A in open-access papers (continued):
Sharing a sentence is not in itself a finding about the gene and the disease.
tumor (continued). "Collectively, these comprehensive data provide robust confirmation that ARID1A serves as a potent suppressor of SCLC tumor growth in vivo." (PMID 41049615, 2025). "We found that patients with low ARID1A expression presented increased levels of p-CHK1S345 within the tumor tissue (p < 0.05)." (PMID 40750787, 2025). "COM exposure led to the downregulation of well-established RCC tumor suppressor genes, including ARID1A, PTEN, and VHL, while significantly increasing TPX2 expression." (PMID 40362354, 2025). "Promoter methylation of at least one HOX related gene (ALX4, CDX2 or HOPX) or ARID1A gene was detected in 83.08% (54/65) of tumor samples." (PMID 40002854, 2025). "In vitro and in vivo investigations manifested that ARID1A inhibited cell survival, proliferation, and tumor growth, functioning as a gatekeeper for cell proliferation and a caretaker of genome stability in SCLC cells." (PMID 41049615, 2025). "Loss of BAF250a expression was highly correlated with ARID1A mutations, suggesting its role as a tumor suppressor." (PMID 40364006, 2025). "Correspondingly, ARID1A mutations correlate with elevated VEGF levels, aggressive tumor phenotype, poor survival, and cisplatin resistance." (PMID 41383608, 2025). "Assessing the RF model’s performance across the 33 TCGA cancer cohorts indicated that for certain genes, like ARID1A, the model achieved high F1 scores across diverse tumour types." (PMID 40775769, 2025). "The altered expression of key genes in immune cells confirms the impact of Arid1a deletion on immune responses within the tumour microenvironment." (PMID 40621620, 2025). "To evaluate the tumor-suppressive role of ARID1A in GC, we performed stable ARID1A knockdown in HGC-27 and AGS cell lines." (PMID 41215803, 2025). "Mechanistically, this process involves suppression of the TGF-β/Smad4 tumor suppressor pathway, establishing an ARID1A-TGF-β-Smad4 axis as critical in preventing biliary carcinogenesis." (PMID 41008893, 2025). "As observed in EAC line cells, the deletion of the ARID1A gene results in tumor cell proliferation, growth, and invasion." (PMID 41369383, 2025). "One of the most common proteins expressed on the outside of tumor cells to evade immune detection when ARID1A is low is PD-L1, which is a protein that binds to the PD-1 protein on T cells and signals them to stop attacking the cancer cell." (PMID 40429787, 2025). "Loss of ARID1A compromises genomic stability, resulting in TOP2A-mediated dsDNA breaks that can accumulate and contribute to tumor progression and genomic instability." (PMID 40750787, 2025). "Nonetheless, our novel findings underscore a significant relationship between Arid1a and IL-33, particularly relevant to the type 2 immunity-dominant tumor microenvironment." (PMID 40761291, 2025). "On the other hand, in tumors, the loss of ARID1A can lead to low differentiation of cells, upregulated PD-L1 expression, suppression of CD8+ T cell activity, and enhanced tumor malignancy." (PMID 40342423, 2025). "Inhibition of Histone Deacetylase 6 (HDAC6) combined with the immune checkpoint blockade (anti-PD-L1) can treat ARID1A-mutated OCCC by enhancing cytotoxic T cell activity and modulating the tumor immune microenvironment." (PMID 40656893, 2025). "The molecular mechanisms indicate that ARID1A overexpression can act as a vital driver of tumor initiation and progression by altering chromatin remodeling, metabolic regulation, and transcriptional reprogramming." (PMID 41514650, 2025). "Although extensive research has established that ARID1A regulates DNA double-strand break repair, replication stress responses, and chromatin structure in other tumor models, comparable mechanistic validation in TNBC models is still lacking." (PMID 41514650, 2025). "ARID1A KO exhibited significant upregulation of cell cycle‐related pathways, including the G2M checkpoint, E2F targets, and mitotic spindle, consistent with ARID1A tumor‐suppressive role." (PMID 40671262, 2025).
tumor (continued). "ARID1A silencing significantly promoted tumor growth, as evidenced by a significant increase in the tumor volume and weight." (PMID 41049615, 2025). "Before we investigated ARID1A loss and IFNγ signaling cytokines, we wanted to explore previous findings connecting MYCN amplification with the cold tumor phenotype." (PMID 40082458, 2025). "A recent elegant study showed that immune evasion in ARID1A mutant tumours is mediated by impaired chromatin accessibility of IFNγ responsive genes, including Th1 chemokines CXCL9, CXCL10 and CXCL11." (PMID 39920335, 2025). "One tumor from each cohort had high tumor mutational burden and microsatellite-instability with PMS2 and ARID1A mutation." (PMID 40634688, 2025). "For example, although ARID1A is a tumor suppressor, certain cancer hallmarks are amplified following the loss of heterozygosity." (PMID 40429787, 2025). "Studies have demonstrated that ARID1A synergizes with MYCN amplification to drive the transition of tumor cells from an adrenergic to a mesenchymal phenotype, thereby enhancing invasive and migratory capacities and accelerating disease progression." (PMID 41001036, 2025). "Transwell migration assay demonstrated that ARID1A knockdown promoted cell migration and inhibited the anti-tumor migration ability of osimertinib." (PMID 40463905, 2025). "Our results demonstrated a significant upregulation of fatty acid metabolism and fatty acid synthase (FASN) in the KAR tumours, with ARID1A directly regulating FASN expression." (PMID 40621620, 2025). "The ARID1A protein has emerged as a pivotal regulator in the pathogenesis of diverse tumor types within oncology research." (PMID 41001036, 2025). "Further investigations demonstrated that ARID1A hypermethylation mediates immune checkpoint inhibition via PD-L1 and significantly reshapes the tumor immune microenvironment (TIME)." (PMID 41215803, 2025). "ARID1A is a critical tumor suppressor that exerts its function by interacting with transcription factors and their co-repressor complexes, particularly recruiting chromatin remodeling activity." (PMID 40699663, 2025). "By regulating the transcription of several key oncogenes or tumor suppressors and multiple other mechanisms, ARID1A is recognized as a bona fide tumor suppressor in various cancer types." (PMID 40369167, 2025). "Pharmacological inhibition or siRNA-mediated depletion of c-MET inhibits the growth of ARID1A-deficient CRC cells in vitro and tumor xenografts in vivo." (PMID 40369167, 2025). "In four patients, longitudinal analyses of subsequent lesions showed the maintenance of most genomic alterations and enrichment in missense or splice variants in PMS2, SMARCA4, ARID1A, AKT1, BMPR1A, and PTEN, indicating the occurrence of tumor evolution." (PMID 41514647, 2025). "Consistent with its role as a tumour suppressor in PDAC, ARID1A mutations, which are mostly deletions or truncations, are found in 5–15% of cases of the disease." (PMID 40723241, 2025). "Three of these cases also exhibited concurrent alterations in the tumour suppressor genes ARID1A, NF1, or RB1, suggesting even poorer prognosis and a need for more intensive follow‐up or more aggressive interventions beyond EGFR TKI monotherapy." (PMID 41015991, 2025).
tumor (continued). "Together, these findings indicate that ARID1B OE can reduce ARID1A chromatin binding at select target genes, potentially contributing to oncogenesis by suppressing ARID1A tumor‐suppressive functions." (PMID 40671262, 2025). "In MDA‐MB‐468 cells, loss of ARID1A significantly promoted cell growth and colony formation, consistent with the known tumor‐suppressive role of ARID1A." (PMID 40671262, 2025). "Current studies and findings show that the role of ARID1A is highly context-dependent, acting as both a tumor suppressor and a tumor promoter depending on the cancer stage, tissue type, and mutational background." (PMID 41514650, 2025). "EMP treatment showed negligible suppressive effects on HCT116 ARID1A+/+ tumor xenografts, whereas it significantly inhibited HCT116 ARID1A−/− xenograft tumor growth." (PMID 41360780, 2025). "ARID1A deficiency potentiates immunotherapy efficacy by elevating PD-L1 expression and TMB, impairing mismatch repair (MMR) function, and remodelling the tumor immune microenvironment (TIME)." (PMID 40463905, 2025). "ARID1A functions as a tumor suppressor, playing a critical role in maintaining chromatin architecture and regulating gene expression." (PMID 40671262, 2025). "At the cancer cell-intrinsic level, ARID1A acts as a tumor suppressor by regulating the cell cycle, signaling pathways, and epithelial-mesenchymal transition (EMT)." (PMID 40406134, 2025). "ARID1A (AT‐interacting domain‐rich protein 1A) is the BAF subunit most frequently mutated in cancer and is a bona fide tumor suppressor." (PMID 41387924, 2025). "The whole-exome sequencing revealed a variety of common oncogenic mutations in the original tumor and HMucBOT-2, including KRAS, ARID1A, ARID1B, and NF1, while CDKN2A remained wild-type." (PMID 40427213, 2025). "ARID1A has been demonstrated to function as a critical tumour suppressor, and studies have suggested its role in repressing potentially carcinogenic gene expression in bladder epithelial cells by maintaining a balance between transcription and translation." (PMID 39779467, 2025). "To further elucidate the tumor-suppressing effect of ARID1A in SCLC in vivo, we assessed the effects of ARID1A on tumor progression in SCLC xenograft models." (PMID 41049615, 2025). "A univariate Cox analysis based on PFS as clinical outcomes revealed that tumor size, lymph node-positive, clinical stage, venous invasion, nerve invasion, serum AFP, ARID1A mutation were prognostic factors for AFPGC (P < 0.05)." (PMID 39928247, 2025). "The restoration of wild-type ARID1A expression shows suppressed cell proliferation and tumor growth, highlighting its potential as a therapeutic target in ARID1A-mutated cancers." (PMID 41514650, 2025). "For example, mutations in SWI/SNF complex subunits, including ARID1A or SMARCA4, are prevalent in a variety of tumor types and enhance the tumor’s epigenetic flexibility and adaptability." (PMID 41155227, 2025). "In our study, ARID1A expression was correlated with the type of tumor according to Lauren classification in both tumors (p = 0.001) and non-tumor tissue (p = 0.002), which is in concordance with the other investigation." (PMID 39796161, 2025). "Patients with tumours showing lower ARID1A and PTEN levels had a poorer survival compared to other patient groups combined (ARID1A low PTEN low median survival 31 months vs all other groups median survival 57 months *p = 0.0303)." (PMID 39885328, 2025). "Recent studies further demonstrate that the loss of ARID1A expression increases EMT (epithelial–mesenchymal transition) markers’ expression, which are associated with enhanced migration and tumor cell aggression." (PMID 41514650, 2025).
tumor (continued). "We found that ARID1A re-expression resulted in a failure to establish tumors in mice, consistent with the role of ARID1A as a tumor suppressor." (PMID 40938753, 2025). "Positive selection of variants of tumour suppressor genes PTEN and ARID1A associates with monoallelic gene loss as confirmed by CRISPR/Cas9 mutagenesis and changes in their downstream effectors." (PMID 39920335, 2025). "EBV-positive tumours show several common mutations such as PI3K catalytic subunit alpha (PIK3CA; 80%), ARID1A (55%) and BCOR (23%) mutations, which have the potential to be treated by targeted therapy." (PMID 41356795, 2025). "To gain molecular insight into Arid1a-mediated epigenetic changes in prostate tumorigenesis, we performed Chromatin Immunoprecipitation Sequencing (ChIP-Seq) on Pb-Cre;Ptenfl/fl tumours to interpret data from transcriptomic analysis." (PMID 39885328, 2025). "Especially, ARID1A gene knockout, combined with overexpressing the KRAS oncogenic mutant allele (or overexpressing AKT) and c-Myc overexpression led to efficient tumor formation." (PMID 40076621, 2025). "Then, in vitro and in vivo investigations using knockdown (KD) and overexpression approaches highlighted ARID1A’s function as a tumor suppressor in SCLC." (PMID 41049615, 2025). "ARID1A has a dual role in oncogenic and tumor-suppressive functions, depending on the type of cancer." (PMID 41049615, 2025). "Physiological role: ARID1A has a key role as a tumor suppressor, as well as a regulator of the DNA repair mechanism, gene expression, and its protein is a member of the SWI/SNF chromatin remodeling complex." (PMID 41369383, 2025). "In metastatic urothelial carcinoma, the status of ARID1A mutation and CXCL13 expression in tumour tissues predicted the clinical responses to immune checkpoint therapy." (PMID 40621620, 2025). "ARID1A deletion results in the recruitment of T cells for anti-tumor immune responses through activation of the cGAS/STING pathway." (PMID 40406134, 2025). "Overall, this data shows that ARID1A mutations are highly recurrent, predominantly disruptive and associated with lower FAS expression in tumor cells in primary human FL." (PMID 39843653, 2025). "To further explore the underlying mechanism that ARID1A exerts as a tumor suppressor in SCLC, we examined the effect of ARID1A on the DNA damage response (DDR)." (PMID 41049615, 2025). "In a recurrent tumor in the parapharyngeal space of the patient discussed in our report, ARID1A G2087R, PRKR1A F200fs∗6, and RAD21 amplification were identified as disease-relevant alterations by genetic testing." (PMID 40777560, 2025). "Next generation sequencing of the tumor at baseline showed microsatellite instability high (loss of MLH1 and PMS2 and TMB 15, ARID1A G801FS*32, KRAS Q6H, PIK3CA N1044K, PTEN R130G, SMARCA4 P109FS*194 and SMARCA4 P316FS*10 mutations)." (PMID 40382524, 2025). "A shift from ARID1A‐ to ARID1B‐bound BAF complexes can result in a switch from tumor‐suppression to oncogenesis action in SWI/SNF chromatin remodelers." (PMID 40671262, 2025). "As an important tumor suppressor gene, the mechanism by which ARID1A affects the expression of SLC7A5 will also be a focus of our next research steps." (PMID 40133832, 2025). "We identified newly emerging mutations in genes that were not covered by our targeted NGS panel such as ATM, NOTCH2, EP300, ARID1A and MAP3K1 and also noticed an increase in tumor mutational burden (TMB) in some cases during progression." (PMID 40973765, 2025). "Having established that Arid1a deletion promotes pancreatic tumourigenesis, we next sought to investigate how these genetic changes influence the tumour microenvironment during cancer progression." (PMID 40621620, 2025).
tumor (continued). "This epigenetic vulnerability underscores the therapeutic relevance of methylation-silenced tumor suppressors like ARID1A." (PMID 41215803, 2025). "These transcriptional changes suggest that ARID1A normally restrains cell proliferation while supporting other metabolic or stress response pathways, consistent with its tumor‐suppressive function." (PMID 40671262, 2025). "ARID1A has also been shown to be a tumour suppressor due to its inhibition of cell cycle, mediation of DNA-repair, and high mutation rates in certain cancers such as ovarian cancer." (PMID 39885328, 2025). "ARID1A loss impairs interferon signaling, facilitating immune evasion, and is associated with increased expression of HDAC6, which promotes tumor cell invasion, migration, and poorer overall survival." (PMID 41383608, 2025). "c-MET specific inhibitor PHA-665752 as well as two other FDA-approved drugs, crizotinib and cabozantinib, selectively inhibited the growth of ARID1A-deficient CRC cells in vitro and in xenograft tumor models." (PMID 40369167, 2025). "We agree that the genetic dosage effect of ARID1A and its biological consequences can vary depending on tissue context, tumour type and species‐specific compensatory mechanisms." (PMID 40621620, 2025). "This pattern suggests a potential “two-hit” inactivation mechanism in gastric carcinogenesis, wherein the tumor-suppressive function of ARID1A is simultaneously disrupted by epigenetic silencing (via promoter hypermethylation) and genetic aberrations." (PMID 41215803, 2025). "Mutational inactivation of ARID1A leads to dysregulation in the PI3K/AKT pathway, WNT pathway, DNA damage response, and tumor immune microenvironment, suggesting ARID1A is a potential therapeutic target in CRC." (PMID 41360780, 2025). "The analysis of the overall survival of GC patients revealed that ARID1A expression in tumor tissues was significantly higher in patients who survived at the time of the study (p = 0.038)." (PMID 39796161, 2025). "With mutations in genes encoding SWI/SNF subunits, including ARID1A, ARID1B, ARID2, PBRM1, SMARCA4, and SMARCB1, collectively occurring in ~20% of all tumor types, SWI/SNF complexes are the most commonly mutated chromatin modulators in human cancer." (PMID 40369167, 2025). "ARID1A, as a tumor suppressor, maintains transcriptional regulation, genomic stability, and cellular differentiation." (PMID 41514650, 2025). "Next, we explored the relationship between the heterogeneous expression of ARID1A and the tumor lymphocyte infiltration." (PMID 38555560, 2024). "In comparison to ARID1A -proficient patients, patients with ARID1A deficiency exhibited a significant increase in the infiltration levels of CD8 + cells, CD163 + cells and FOXP3 + cells within the tumor tissue." (PMID 38555560, 2024). "ARID1A is involved in the DSB process in tumor cells, similar to the role BRCA plays in tumor cells." (PMID 38347608, 2024). "In this study, we observed that the small-molecule RITA selectively inhibited the growth of ARID1A-deficient CRC cells in vitro and of tumor xenografts in vivo." (PMID 38811536, 2024). "Although ARID1A upregulation exacerbates tumour development, mice having liver-specific homozygous or heterozygous ARID1A deletion were imperviable to tumour initiation." (PMID 39471843, 2024).